FLT4 (fms related receptor tyrosine kinase 4)
Diseases named in the same sentence as FLT4 in open-access papers (continued):
Sharing a sentence is not in itself a finding about the gene and the disease.
colorectal cancer (30 papers, 2003 to 2025). A primary or metastatic malignant neoplasm that affects the colon or rectum. "Given FLT4’s believed function as an oncogene playing a role in invasion and metastasis, further investigation should be made as to the relevancy of this variant or FLT4’s role in pathogenicity in colorectal cancer." (PMID 30709382, 2019). "FLT4 frameshift variant P30fs was observed in colorectal cancers in 6 of the 7 samples it appeared, and the 2 COSMIC reported cases were also colorectal cancer." (PMID 30709382, 2019). "In sum, these findings provide evidence that FLT4 (VEGFR3/CD310) expression could serve as a valuable prognostic biomarker to stratify colorectal cancer patients and select those who will likely respond to fruquintinib-based treatments." (PMID 41459512, 2025). "These preliminary data suggest that VEGFR3/FLT4/CD310 may be a potential prognostic biomarker for colorectal carcinoma, warranting further clinical investigation to validate these findings." (PMID 41459512, 2025). "Although somatic variants of FLT4 in solid malignancies are not commonly reported, mutations in colorectal cancer and non-small cell lung cancer have been documented." (PMID 34638295, 2021). "This might also indicate a potential tumor suppressor role for FLT4 gene in colorectal cancer." (PMID 30709382, 2019). "In humans, genistein inhibited MMP-2 and Fms-related tyrosine kinase 4 (FLT4; vascular endothelial growth factor receptor 3) in CRC (colorectal cancer) tumors of mice." (PMID 34336089, 2021).
lung carcinoma (29 papers, 2006 to 2025). "CNTN1 was discovered as an immediate downstream effector of the vascular endothelial growth factor (VEGF)C-VEFGR3/Flt4 that induced invasion and metastasis in lung cancer via the Src/p38 MAPK-mediated C/EBP signaling pathway." (PMID 32752094, 2020). "For instance, while the VEGFC/Flt4 pathway unregulated CNTN1 expression in lung cancer, CNTN1 upregulation in prostate cancer is an outcome of the conversion of non-CSC PC cells to PCSC and CNTN1 in turn contributes to PCSC-derived metastasis." (PMID 32752094, 2020). "Our identification of FLT4 as an important regulator of cancer metastasis is supported by the work of others who report that the VEGF-C/FLT-4 axis promotes lung cancer cell migration and invasion." (PMID 25605009, 2015). "FLT4-targeted drugs famitinib, catequentinib, sunitinib, and axitinib are undergoing phase I/II trials for various cancers, including nasopharyngeal carcinoma, renal cell carcinoma, colorectal adenocarcinoma, lung cancer, and prostate cancer." (PMID 41261599, 2025). "Both VEGFA and its receptor FLT4 (VEGFR-3) were altered during splicing in lung cancers LUAD and LUSC, which might modulate angiogenesis through splicing control." (PMID 31024612, 2019). "For instance, in lung cancer, IGF2BP2 increases the stability of fms-related tyrosine kinase 4 (FLT4; also known as VEGFR3) or thymidine kinase 1 (TK1) mRNA, leading to tumor angiogenesis and aggressiveness." (PMID 39098905, 2024). "Thus, further studies are needed to investigate whether B-Myb activates ERK and Akt signaling pathways at least partially though up-regulation of FLT4, COL11A1, and NID1 in lung cancer cells." (PMID 28555007, 2017).
gastric cancer (24 papers, 2003 to 2025). A primary or metastatic malignant neoplasm involving the stomach. "In vitro studies found that the knockdown of Flt4 in human MKN45 gastric cancer cells with short hairpin RNA directly downregulated CNTN1 expression, which validates the role of CNTN1 in the VEGFC-VEFGR3/Flt4 axis." (PMID 32752094, 2020).
angiosarcoma (19 papers, 2012 to 2025). A malignant tumor arising from the endothelial cells of the blood vessels. "FLT4 is another well-studied gene mutation in angiosarcoma, associated with angiosarcomas of the head and neck, as well as secondary angiosarcomas due to radiation." (PMID 41301029, 2025). "Co-amplification of FLT4 (encoding VEGFR3) on 5q35 was detected in 25 % of radiation-induced angiosarcoma." (PMID 26462621, 2015). "The FLT4 gene, which maps to chromosome on 5q35 and encodes for VEGFR3, is reported in approximately 25% of secondary angiosarcomas." (PMID 34068344, 2021). "Genetic analysis of angiosarcomas uncovered mutations in genes such as Myc, FLT4, KDR, PLCγ and PTPRB9,10, and emerging evidence also implicates miRNAs in angiosarcoma pathogenesis." (PMID 31004117, 2019). "Both FLT4 and MYC gene abnormalities can potentially be used as molecular diagnostic tool to distinguish from atypical vascular lesions (AVL) and secondary angiosarcoma." (PMID 26462621, 2015). "In cases of secondary angiosarcoma, FLT4 amplification typically co-occurs with MYC." (PMID 41301029, 2025). "The pathogenesis of angiosarcoma is probably also related to other genes, including CIC gene rearrangement, increased expression of the MYC gene and FLT-4 gene, and mutations of PTPRB and PLCG1, but the present study focused on the PD-1/PD-L1 and PI3K/mTOR signaling pathways." (PMID 34397726, 2021). "RAS had more frequent MYC, FLT4, CRKL, HRAS, and KMT2D alterations than sporadic angiosarcomas." (PMID 38256700, 2024). "Moreover, Fms Related Tyrosine Kinase 4 (FLT4) and MYC co-amplification was observed in 25% of secondary angiosarcomas." (PMID 28056866, 2017).
primary lymphedema (19 papers, 2010 to 2026). A congenital condition that results in swelling in the arms or legs, and can occur during adolescence or adulthood. "Primary lymphedema, a rare inherited autosomal dominant disorder, is initially characterized by mutations in FLT4 (which encodes VEGFR3)." (PMID 38172098, 2024). "Here we report compound heterozygotes variants in FLT4 of a Chinese family associated with primary lymphedema display autosomal recessive inheritance." (PMID 37035731, 2023). "Mutations in the transcription factor-coding gene SOX18, the growth factor-coding gene VEGFC and its receptor-coding gene VEGFR3/FLT4 cause primary lymphedema in humans." (PMID 37759531, 2023). "Our results suggests the possibility of an autosomal recessive inherited form of primary lymphedema resulting from variants of FLT4 encoding the vascular endothelial growth factor receptor-3." (PMID 37035731, 2023). "In preceding investigations involving FLT4 sequence analysis conducted on individuals presenting with primary lymphedema, we identified several rare genetic variants that possess the potential to modulate the functional activity of VEGFR3, including the heterozygous variant c.3175G>C (p.A1059P)." (PMID 41614898, 2026). "In previous analyses of the FLT4 sequence in patients with primary lymphedema, we identified several rare genetic variants that may affect the functional activity of VEGFR3, including the heterozygous variant c.3175G>C (p.A1059P)." (PMID 41614898, 2026). "Mutations in the VEGFR3 (FLT4) gene in humans induces hereditary primary lymphedema." (PMID 35355722, 2022). "VEGFC-dependent VEGFR3 phosphorylation and FLT4 expression were reduced in cells with c.3175G>C FLT4 variant compared to wild-type, confirming the pathogenic role of c.3175G>C in primary lymphedema." (PMID 41614898, 2026).
prostate carcinoma (18 papers, 1999 to 2025). A carcinoma that arises from epithelial cells of the prostate gland. "Mutations in FLT4 have been associated with sentinel lymph node metastases in prostate cancer and FLT4 plays a critical role in prostate lymphangiogenesis." (PMID 38067373, 2023). "FLT4 is a VEGF receptor that is implicated in angiogenesis while FRS3 is known to regulate prostate cancer progression." (PMID 25944692, 2015). "We observed enrichment of mutations in several genes including understudied genes such as EYA1, CSMD3, FLT4, NCOR2, and PCDH15 and found that mutations in EYA1 and CSMD3 are associated with a poor outcome in prostate cancer." (PMID 38067373, 2023). "Compound 4b only inhibited seven other kinases (Aurora A, KDR/VEGFR2, SGK1, FLT4/VEGFR3, PIM1, PKD2, and LCK), to similar extent as CK2, and turned out to be cell-permeable and capable of inducing apoptosis in the prostate cancer cell LNCaP." (PMID 29462988, 2018). "The association of FLT4 and PCDH15 with prostate cancer metastases has not been previously reported." (PMID 38067373, 2023).
cervical cancer (17 papers, 2005 to 2024). A primary or metastatic malignant neoplasm involving the cervix. "Vascular endothelial growth factor receptor 3 (FLT4) enhances cervical cancer migration and invasion." (PMID 38259849, 2023). "Recent years the Flt-4 has been shown to be expressed in a variety of human malignancies, including cervical cancer." (PMID 20429915, 2010). "Our study explored the roles of VEGF-C, VEGF-D, and FLt-4 in the lymphatic metastasis of early-stage cervical cancer." (PMID 19589137, 2009). "In this study, we employed immunohistochemical (IHC) staining to detect the expression of VEGF-C, VEGF-D, and Flt-4 in early-stage cervical carcinoma (Ia-IIa)." (PMID 19589137, 2009). "Immunohistochemical (IHC) staining with the antibodies against VEGF-C, VEGF-D, and Flt-4 was used to examine the expression of them in 97 cases of early-stage cervical carcinoma (Ia-IIa)." (PMID 19589137, 2009). "The IHC signals of VEGF-C, VEGF-D, and their receptor Flt-4 were mostly localized in the cytoplasm of the cancer cell in the examined cervical carcinoma samples and the positively stained cells showed a brown-yellow color in the cytoplasm." (PMID 19589137, 2009). "Our findings on the presence of Flt-4 expression in the majority of intraductal tumour cells also suggest an autocrine growth-stimulatory pattern of VEGF-C via Flt-4 as described for cervical cancer." (PMID 15841074, 2005). "Therefore, it was speculated that VEGF-C, VEGF-D and Flt-4 could be involved in the process of phenotypic transition to lymphangiogenesis and could facilitate lymphatic metastasis in the early stages of cervical cancer." (PMID 19589137, 2009). "Our literature search, as well as published meta-analyses and reviews, gives grounds for stating that the involvement of FLT4, MET, and SLUG in cervical cancer pathogenesis has been poorly investigated as contrasted with other tumor types." (PMID 32899940, 2020).
ovarian carcinoma (16 papers, 2003 to 2025). A malignant neoplasm originating from the surface ovarian epithelium. "The expression of two other angiogenesis-related genes [i.e., KDR (kinase insert domain receptor) and FLT4 (FMS related tyrosine kinase 4)] was significantly decreased in ovarian cancer cells after treatment with fucoidan and chemotherapeutics." (PMID 37233501, 2023). "Similarly, treatment with fucoidan repressed the mRNA expression of angiogenesis related genes including VEGFA, VEGFB, VEGFC, VEGFD, FLT-1, FLT-4, and KDR in the ovarian cancer cells." (PMID 31936539, 2020). "Of note, previous reports showed that COL11A1 elevates phosphorylated Akt in ovarian cancer cells by stabilizing PDK1, and FLT4 participates in the induction of phosphorylation of extracellular signal-regulated kinase (ERK) 1/2 as well as in the proliferative and migratory ability of SG-2 cells." (PMID 28555007, 2017). "In the present study, the molecular markers of progenitors in cells isolated from ascites and tumor tissues of patients with advanced or recurrent ovarian cancer were the highly expressed EGFR and Flt-4 (VEGF receptor), which are important during tumor angiogenesis and metastasis." (PMID 22330345, 2012).
lung adenocarcinoma (13 papers, 2007 to 2025). A carcinoma that arises from the lung and is characterized by the presence of malignant glandular epithelial cells. "Previous study had suggested that IGF2BP2 elevated FLT4 stability via m6A modification, thus accelerating angiogenesis and metastasis of lung adenocarcinoma cells." (PMID 39014364, 2024). "The genetic alterations and gene expression changes in the BIRC5, HIF1A, and FLT4 oncogenes in lung adenocarcinoma (LUAD) were analyzed using muTarget software." (PMID 37509650, 2023). "In addition, IGF2BP2 enhances the RNA stability of Fms Related Tyrosine Kinase 4 (FLT4) via m6A modification, activating the PI3K-Akt signaling pathway in lung adenocarcinoma (LUDA)." (PMID 38711100, 2024).
colon carcinoma (12 papers, 2003 to 2025). "Moreover, elevated VEGFR3/FLT4/CD310 levels are associated with poorer overall survival in two small exploratory series of colon carcinoma patients." (PMID 41459512, 2025). "In contrast, we observed increased FLT4 expression in metastatic samples (compared to healthy tissue or tumoral samples) and in more aggressive histological mucinous subtype from colon carcinoma patients." (PMID 41459512, 2025). "To provide preliminary evidence on the possible use of VEGFR3/FLT4/CD310 as a prognostic marker in colon carcinoma, we analyzed publicly available gene expression datasets." (PMID 41459512, 2025). "Moreover, we observed increased survival in samples from colon carcinoma patients with low FLT4 expression." (PMID 41459512, 2025). "Fruquintinib has emerged as a specific VEGFR3/FLT4/CD310 inhibitor that potently inhibits angiogenesis and tumor growth in preclinical models and clinical trials of colon carcinoma, with recent approvals for its use as a third-line therapy in China, the USA, Canada, and several European countries." (PMID 41459512, 2025).
renal cell carcinoma (11 papers, 2009 to 2025). "Despite this, just 12 h treatment with CDF resulted in prolonged inhibition of lymphangiogenesis via continued inhibition of the Vegfc/Flt4/Erk pathway compared with the FDA approved standard of care molecule in renal cell carcinoma and imatinib-resistant gastrointestinal stromal tumour, SM." (PMID 34206901, 2021).
congenital primary lymphedema (10 papers, 2006 to 2024). "PL can develop in utero and be congenital, such as in Nonne-Milroy disease caused by VEGFR3 (FLT4 gene) mutations, but it can also appear later in life, during puberty or adulthood, such as in patients with EPHB4-related PL." (PMID 38820174, 2024).
Hypertension (10 papers, 2011 to 2024). The presence of chronic increased pressure in the systemic arterial system. "This relationship is consistent with the VIMP analysis results, where VEGFR family kinases including FLT1 (VEGFR1), VEGFR2, and FLT4 (VEGFR) have been identified as the top 1, 2, and 15 kinases associated with hypertension." (PMID 35896580, 2022). "Angiotensin II infusion significantly increased the mRNA expression levels of lymphatic endothelial markers Lyve1, Pdpn, Vegfc, and Flt4 in kidney, which is consistent with previous reports and represents an endogenous expansion in response to systemic hypertension." (PMID 33200983, 2020).
myocardial infarction (10 papers, 2018 to 2025). Gross necrosis of the myocardium, as a result of interruption of the blood supply to the area, as in coronary thrombosis. "However, lymphangiogenesis blockade in heart using Flt4 knockout or Vegfc/Vegfd double knockout animals did not exacerbate cardiac dysfunction after myocardial infarction (MI), indicating that the beneficial effects observed with VEGFCC156S in MI could be mediated by alternative mechanisms." (PMID 38915742, 2024).
pancreatic cancer (10 papers, 2013 to 2025). "KRSA and UKA directionality metrics (Figure A3, Table A1) demonstrate increased FLT4 activity in pancreatic cancer compared to wild-type controls." (PMID 33213062, 2020). "VEGFR-3, also known as fms related receptor tyrosine kinase 4 (FLT4), has been explored as a target for pancreatic cancer therapy with significantly upregulated FLT4 expression documented in pancreatic cancer specimens." (PMID 33213062, 2020). "Research on targeted therapies for FLT4 and TGFBR2 mutations remains limited in pancreatic cancer." (PMID 40994638, 2025).